RNU6-32P (RNA, U6 small nuclear 32, pseudogene)
Synonyms: RNU6-32
Gene: Small nuclear RNA gene on chromosome 4 (39,297,605 to 39,297,711, reverse strand). Ensembl gene ENSG00000206675.
Homologues: Orthologues: mouse Gm22821 (100% identical), rat U6 (100% identical), pig U6 (89% identical). Paralogues in human: RNU6-12P (100% identical), RNU6-13P (100% identical), RNU6-1 (99% identical), RNU6-17P (99% identical), RNU6-18P (99% identical), RNU6-2 (99% identical), RNU6-3P (99% identical), RNU6-4P (99% identical), RNU6-5P (99% identical), RNU6-6P (99% identical), RNU6-9 (99% identical), RNU6-25P (98% identical), and 1290 more.